ADAMTS10 (ADAM metallopeptidase with thrombospondin type 1 motif 10)
Diseases named in the same sentence as ADAMTS10 in open-access papers (continued):
Sharing a sentence is not in itself a finding about the gene and the disease.
melanoma (1 paper, 2025). A malignant, usually aggressive tumor composed of atypical, neoplastic melanocytes. "Human ADAMTS10 is not expressed in melanoma in the TCGA database, and it is not commercially available in recombinant form." (PMID 40064965, 2025).
metastatic colorectal cancer (1 paper, 2023). "Besides, ADAMTS10 is frequently mutated in metastatic colorectal cancer, and mutated ADAMTS10 transcripts are actively expressed in the corresponding tumors implicating a possible role for ADAMTS10 in tumor metastasis." (PMID 37822877, 2023).
mitral valve prolapse (1 paper, 2020). A fairly common and often benign valvular heart disorder characterized by redundancy or hooding of mitral valve leaflets so that they prolapse into the left atrium, often causing mitral regurgitation. "Expression of ADAMTS10 was indeed observed in the leaflets of the aortic valve and WMS1 due to ADAMTS10 mutations can result in mitral valve prolapse." (PMID 32290605, 2020).
mitral valve regurgitation (1 paper, 2025). "Pulmonary, aortic, and mitral valve stenosis, as well as mitral valve regurgitation have all been reported in patients with WMS, which could be exacerbated when ADAMTS10 and ADAMTS17 are both absent." (PMID 41034152, 2025).
omphalocele (1 paper, 2022). Omphalocele is an embryopathy classified in the group of abdominal celosomias and is characterized by a large hernia of the abdominal wall, centered on the umbilical cord, in which the protruding viscera are protected by a sac. "Adamts6-/-;Adamts10-/- embryos demonstrated markedly more severe external anomalies than Adamts6-/- mutants including subcutaneous hemorrhage, micrognathia and an omphalocele, along with more severe forelimb and hindlimb dysmorphology." (PMID 35503090, 2022).
connective tissue disorder (7 papers, 2010 to 2023). A disease involving the connective tissue. "Four members of the ADAMTS superfamily, ADAMTS10, ADAMTS17, ADAMTSL2 and ADAMTSL4 have been implicated in connective tissue disorders, including ADAMTSL2, the cause of GD." (PMID 20862248, 2010).
tumor (6 papers, 2012 to 2024). "The only association we observed in our study between PIK3CA mutation status and the levels of studied proteins was the decreased ADAMTS10 protein concentration in the PIK3CA-mutated tumor group." (PMID 39329961, 2024). "The genes significantly associated with tumor size were ADAMTS10 (p = 0.004, r = 0.585) and ARID1A (p = 0.004, r = 0.585)." (PMID 35055428, 2022). "Therefore, the observed associations between the expressions of the SEMA7A, SEMA4D, ADAM8, and ADAMTS10 in tumor groups with KRAS, NRAS, BRAF, PIK3CA, and AKT mutations require validation in larger study cohorts." (PMID 39329961, 2024). "We subsequently investigated the potential associations between the expression levels of SEMA7A, SEMA4D, ADAM8, and ADAMTS10 proteins and the characteristics of tumor size (T), lymph node involvement (N), metastasis (M), and disease stage." (PMID 39329961, 2024). "ADAMTS10 and ARID1A mutations were observed simultaneously in the patient (P18) who had the largest tumor size (14.5 cm) among the 22 patients (size of tumors without mutation, mean: 6.2 cm, median: 5.5 cm)." (PMID 35055428, 2022). "The finding that ADAMTS10 mutations were associated with large tumor size has not been reported in other studies." (PMID 35055428, 2022). "To further assess the impact of ADAMTS8, we utilized the data of the TCGA cohort and discovered a lower level of ADAMTS8 in tumor parts and other members of the ADAMTS family, except for ADAMTS10." (PMID 35743687, 2022).
genetic disorders (1 paper, 2012). "All together, these related genetic disorders suggest that specific ADAMTSL (at least ADAMTSL-2 and -4) and ADAMTS (ADAMTS-10 and -17) proteins modulate fibrillin-1 function in the skeleton, skin, joints, muscle, and eye." (PMID 22242013, 2012).
infection (1 paper, 2023). The state of being infected such as from the introduction of a foreign agent such as serum, vaccine, antigenic substance or organism. "These are involved in smooth-muscle function (FGFR1, GATA5 and STIM1), tissue organization (ADAMTS10), alveolar and epithelial function (ABCA3 and CLDN18), and inflammation and immune response to infection (CFH, CYTL1, HMCN1, LRBA and STIM1)." (PMID 36914875, 2023).
ADAMTS10 also shares sentences with these, for which no sentence is quoted: cancer (3 papers); brachydactyly (2); Microspherophakia (2); blood disorders (1); cervical cancer (1); colorectal adenocarcinoma (1); Em (1); geleophysic dysplasia (1); lens disorder (1); mitral valve stenosis (1); myopia (1); ocular hypertension (1); optical neuropathy (1); osteoarthritis (1); osteosarcoma (1); ovarian carcinoma (1); Peters plus syndrome (1); polyneuropathy (1); pulmonary stenosis (1); retinal degeneration (1); retinitis pigmentosa (1); Stenosis (1); thrombotic thrombocytopenic purpura (1); Traboulsi syndrome (1).